KMT2C (lysine methyltransferase 2C)
Description:
Histone methyltransferase that catalyzes methyl group transfer from S-adenosyl-L-methionine to the epsilon-amino group of 'Lys-4' of histone H3 (H3K4). Part of chromatin remodeling machinery predominantly forms H3K4me1 methylation marks at active chromatin sites where transcription and DNA repair take place. Likely plays a redundant role with KMT2D in enriching H3K4me1 mark on primed and active enhancer elements.
Synonyms: HALR; KIAA1506; MLL3; KLEFS2
Tractability: Small molecule: a structure with a bound ligand is known; a high-quality ligand is known. PROTAC: ubiquitination databases record sites on it; its protein half-life has been measured.
Target class: Writer; Protein methyltransferase; Epigenetic regulator
Gene: Protein-coding gene on chromosome 7 (152,134,922 to 152,436,644, reverse strand). Ensembl gene ENSG00000055609.
Subcellular location: Nucleus
Subcellular location (Human Protein Atlas): Nucleoplasm; Cytosol
Pathways (Reactome):
Gene expression (Transcription): Epigenetic regulation of gene expression by MLL3 and MLL4 complexes; Formation of WDR5-containing histone-modifying complexes; MLL4 and MLL3 complexes regulate expression of PPARG target genes in adipogenesis and hepatic steatosis; RUNX1 regulates genes involved in megakaryocyte differentiation and platelet function
Chromatin organization: PKMTs methylate histone lysines
Developmental Biology: Activation of anterior HOX genes in hindbrain development during early embryogenesis
Immune System: Regulation of PD-L1(CD274) transcription
Gene Ontology:
Molecular function: histone H3K4 methyltransferase activity; histone H3K4 monomethyltransferase activity; histone methyltransferase activity; protein binding; RNA binding; transcription coactivator activity
Biological process: positive regulation of transcription by RNA polymerase II; chromatin remodeling; regulation of DNA-templated transcription
Cellular component: cytosol; histone methyltransferase complex; MLL3/4 complex; nucleoplasm; nucleus
Genetic constraint (gnomAD): Loss-of-function variants: 61 observed, 373.8 expected, observed/expected ratio (o/e) 0.16, 90% interval 0.13 to 0.2. The upper end of that interval is the gene's LOEUF score, 0.2, which puts it in group 1 of 6, group 1 being the genes least tolerant of losing a copy. Missense variants: 4,346 observed, 5,197.2 expected, observed/expected ratio (o/e) 0.84, 90% interval 0.81 to 0.86. Synonymous variants: 1,823 observed, 1,847.2 expected, observed/expected ratio (o/e) 0.99, 90% interval 0.95 to 1.03.
Gene-disease validity (ClinGen):
ClinGen rates the evidence that KMT2C causes each of these diseases.
syndromic intellectual disability (autosomal dominant): Definitive. A intellectual disability that is part of a larger syndrome.
Cancer hallmarks: cell replicative immortality (suppresses); genome instability and mutations (suppresses); suppression of growth (promotes); proliferative signalling (promotes or suppresses); invasion and metastasis (suppresses)
Homologues: Orthologues: chimpanzee KMT2C (98% identical), macaque KMT2C (98% identical), rabbit KMT2C (87% identical), pig KMT2C (86% identical), mouse Kmt2c (85% identical), rat Kmt2c (85% identical), guinea pig KMT2C (84% identical), tropical clawed frog kmt2c (62% identical), zebrafish kmt2ca (52% identical), zebrafish kmt2cb (47% identical), Caenorhabditis elegans set-16 (14% identical), Drosophila melanogaster trr (14% identical), and 16 more. Paralogues in human: KMT2D (35% identical), KMT2A (11% identical), KMT2B (9% identical), SETD1B (7% identical), SETD1A (6% identical), ASH1L (4% identical), EHMT1 (4% identical), EHMT2 (4% identical), NSD1 (4% identical), SETBP1 (3% identical), NSD3 (3% identical), NSD2 (3% identical), and 7 more.
Diseases named in the same sentence as KMT2C in open-access papers:
KMT2C is named in the same sentence as 209 diseases in open-access papers, as found by Europe PMC text mining. Sharing a sentence is not in itself a finding about the gene and the disease. The quoted sentences say what the papers report.
breast carcinoma (95 papers, 2012 to 2026). "Loss-of-function mutations in lysine methyltransferase 2 (KMT2C) are frequently observed in breast cancer and are significantly associated with enhanced tumour heterogeneity, aggressive clinical behaviour, and poor prognosis." (PMID 41674102, 2026). "KMT2C mutations have been detected in a variety of tumors, including hepatocellular carcinoma, breast cancer, colon cancer, bladder cancer, myelodysplastic syndromes and acute myeloid leukemia (AML)." (PMID 39165358, 2024). "Other genes that were frequently mutated in breast cancer included KMT2C, KMT2D, and ARID1A, which were involved in epigenetic regulation." (PMID 38539518, 2024). "KMT2C is frequently mutated in a variety of human cancers, including hepatocellular carcinoma, non-small-cell lung cancer, and breast cancer." (PMID 39165358, 2024). "According to cBioportal, KMT2C is frequently mutated in a variety of cancer types such as breast cancer (~ 12%), melanoma (~ 45%), colon cancer (~ 14%) and hepatocellular carcinoma (50%)." (PMID 39165358, 2024). "Previous studies have shown that KMT2C is mutated in a variety of cancers, including osteosarcoma, acute myeloid leukemia, breast cancer, and gastric cancer." (PMID 36596842, 2023). "Low expression of KMT2C (probe 232940_s_at) was strongly associated with better RFS on breast cancer patients treated with any therapy, in this way supporting our mouse data." (PMID 36933062, 2023). "The loss of KMT2C promotes breast cancer cell reprogramming by downregulating H3K4me1 and upregulating FOXA1-AP-1 binding." (PMID 35453496, 2022). "KMT2C is one of most mutated or deleted genes in ER+ breast cancer patients, and is associated with shorter disease-free survival upon estrogen deprivation with AIs." (PMID 35774123, 2022). "KMT2C is frequently mutated in HR-positive breast cancer and associated with shorter PFS under anti-estrogen therapy." (PMID 34504096, 2021). "In breast cancer tissues, comprehensive DNA sequencing revealed that the genes encoding MLL3 (KMT2C) and MLL4 (KMT2D) were two of the most frequently mutated cancer driver genes." (PMID 31897900, 2020). "Within the H3K4 methyltransferase family, KMT2C is by far the most commonly mutated member with a frequency of approximately 8% in TCGA breast cancer samples." (PMID 29755131, 2018). "To examine the mechanisms of KMT2C-mediated regulation of ER+ breast cancer proliferation, we analyzed the effect of its loss upon established gene expression signatures of ligand-activated ERα." (PMID 29755131, 2018). "We conclude that KMT2C is a key regulator of ERα activity whose loss uncouples breast cancer proliferation from hormone abundance." (PMID 29755131, 2018). "Together, these data suggest that KMT2C loss is likely to have complex effects on the clinical behaviors of breast cancers." (PMID 29755131, 2018). "Furthermore, we discuss emerging therapeutic strategies for KMT2C-deficient breast cancers, such as epigenetic modulators (EZH2 inhibitors, KDM6A inhibitors, and BET inhibitors), DNA damage response (DDR)-targeting agents, and pathway-specific inhibitors." (PMID 41674102, 2026). "Furthermore, KMT2C serves as a driver gene that promotes tumor progression in breast cancer, and high mutation rates of KMT2C have been identified in various cancer types, particularly in NB." (PMID 39338204, 2024). "For example, a loss of H3K4 methyltransferase KMT2C (also known as MLL3) in breast cancer cells may promote bidirectional movements across the epithelial mesenchymal spectrum depending on the base line state of the cells." (PMID 37504297, 2023). "KMT2C encodes a histone methyltransferase, thus the high mutation frequency of KMT2C observed in this study suggests the role of epigenetic dysregulation in breast cancer." (PMID 35740538, 2022).
breast carcinoma (continued). "Nevertheless, KMT2C and other lysine methyltransferases have been implicated in breast cancer pathology, argued as potential drivers in large-scale sequencing studies of primary tumors and KMT2C mutations specifically may confer hormone therapy resistance in breast cancer models." (PMID 33407744, 2021). "Our data, which demonstrate that KMT2C is commonly mutated and that its deletion is significantly associated with shorter patient survival, suggests that KMT2C might function as a tumor suppressor in breast cancer." (PMID 25537518, 2015). "These insights not only elucidate the complex biological functions of KMT2C in breast cancer but also provide a rationale for developing precision therapies tailored to KMT2C-mutant tumours." (PMID 41674102, 2026). "For MPD, frequent mutations in chromatin remodeling genes, such as lysine methyltransferase 2C (KMT2C) and AT-rich interaction domain 2 (ARID2), are well-documented, aligning with its strong association with underlying breast carcinoma." (PMID 40230781, 2025). "KMT2C and KMT2D are histone methyltransferases responsible for the monomethylation of H3K4 and are frequently mutated in cancer, such as breast cancer." (PMID 40032852, 2025). "It has been reported that the KMT2C and MLL4 genes are frequently mutated in many different forms of cancer, some of which include bladder cancer, breast cancer, colon cancer, gastric cancer, liver cancer, medulloblastoma, and non-Hodgkin lymphoma." (PMID 38392574, 2024). "Common breast cancer mutations in the PIK3CA, GATA3 and KMT2C genes are significantly more prevalent in ER-positive/HER2-negative/low proliferation/luminal A cancers compared to the claudin-low group." (PMID 37345027, 2023). "We decided to study the KMT2C role in the context of mouse mammary tumours driven by the well-established breast cancer oncogenic drivers Erbb2/Neu, Myc and PIK3CAH1047R." (PMID 36933062, 2023). "Taken together, our data demonstrate that KMT2C acts as a strong tumour suppressor in breast cancer." (PMID 36933062, 2023). "In agreement with several lines of evidence from various cancers, our study demonstrates that KMT2C acts invariably as a tumour suppressor in breast cancer, since tumours that lack KMT2C became palpable significantly earlier than the WT counterparts." (PMID 36933062, 2023). "Despite the recent interest in epigenetic modifiers as promising druggable targets in cancer, our knowledge on the role of KMT2C in breast cancer is still limited." (PMID 36933062, 2023). "As a key regulator of ERα activity, disrupted KMT2C contributes to hormone-driven breast cancer proliferation." (PMID 35740538, 2022). "Based on the TCGA data, the most frequently altered gene in breast cancer was KMT2C (12%), and the TTN gene (17%) in ovarian cancer." (PMID 35893033, 2022). "To date, the contribution of KMT2C to carcinogenesis has most extensively been studied in breast cancer (BCa), which is biologically similar to PCa due to its dependence on steroid hormone signalling." (PMID 35354467, 2022). "For instance, loss of KMT2C (namely MLL3), one of the six members of the SET family of histone lysine methyltransferases, is reported to drive hormone independence in ER+ breast cancer." (PMID 35774123, 2022). "After prognosis analysis, we found four genes (AKT1, ERBB2, KMT2C, and USP34) associated with survival of breast cancer." (PMID 34408553, 2021). "After prognosis analysis, we found four genes (AKT1 (AKT serine/threonine kinase 1), ERBB2 (Erb-B2 receptor tyrosine kinase 2), KMT2C (lysine methyltransferase 2C), and USP34 (ubiquitin specific peptidase 34)) associated with survival of breast cancer." (PMID 34408553, 2021).
breast carcinoma (continued). "In this study, the data from Thai TNBC would contribute much-needed information from Asian patients to breast cancer genome landscape and provide another evidence on role of KMT2C in breast carcinogenesis." (PMID 30828495, 2019). "In order to test the function of KMT2C in breast cancer, we cloned two short hairpins against KMT2C (shKMT2C)." (PMID 29755131, 2018). "Here, we investigated the role of KMT2C in breast cancer pathogenesis and found it to be an essential ERα coactivator." (PMID 29755131, 2018). "Here, we identify the H3K4 methyltransferase KMT2C as necessary for hormone-driven ERα activity and breast cancer proliferation." (PMID 29755131, 2018). "We found that for seven HMTs (KMT2C, SETDB2, SETD2, SETMAR, PRDM1, PRDM5, and PRDM8), copy number amp/gain or deletion was significantly associated (p<0.05) with shorter survival in breast cancer patients." (PMID 25537518, 2015). "In addition, the LncRNA HOTAIR, which is highly expressed in tumors such as breast cancer, can mediate oncogene silencing by interacting with KMT2C, and its mechanism of action is also related to promoter activity." (PMID 39165358, 2024). "To study the tumour suppressor role of KMT2C in breast cancer, we generated mouse models of Erbb2/Neu, Myc or PIK3CA-driven tumorigenesis, in which the Kmt2c locus is knocked out specifically in the luminal lineage of mouse mammary glands using the Cre recombinase." (PMID 36933062, 2023). "Collectively, our findings solidify the role of KMT2C as a tumour suppressor in breast cancer and identify dependencies that could be therapeutically amenable." (PMID 36933062, 2023). "In breast cancer, KMT2C plays a role in the transcriptional control of oestrogen-regulated genes." (PMID 36933062, 2023). "Besides, KMT2C is regarded as a tumor suppressor, and deletion of this gene is correlated with unfavorable prognosis of breast cancer, acute myeloid leukemia, and gastric adenocarcinoma." (PMID 35847355, 2022). "KMT2C promotes E2-stimulated ERα activity and breast cancer proliferation." (PMID 35453496, 2022). "Four genes (AKT1, ERBB2, KMT2C, and USP34) were associated with survival of breast cancer." (PMID 34408553, 2021). "Notably, in our cohort a gene reported as less frequently mutated in breast cancer, KMT2C (MLL3), showed the second highest mutation count." (PMID 33168853, 2020). "Together this data suggests that KMT2C may act as a breast cancer tumor suppressor and might be a candidate regulator of H3K4me in these tumors." (PMID 29755131, 2018). "Similar to the brc-1 ortholog BRCA1, HORMAD1, SETD1A, KMT2C, and KM2D/MML4 have all been linked to breast cancer, suggesting that these genetic interactions may be conserved in human cells." (PMID 28506208, 2017).
breast carcinoma (continued). "Indeed, KMT2C is a key regulator of ERα activity and anti-estrogen response in breast cancer." (PMID 36243974, 2022). "Additionally, we identified the alterations of epigenetic targets, such as SWI/SNF related genes (SMARCA2, SMARCA4, SMARCA5) or histone modifiers (KMT2C or KMT2D), breast cancer-associated oncogenes (MYCN or MAPKs), or genes that are involved in drug-resistance (ESR1 and PIK3CA/B)." (PMID 31216647, 2019). "Although it is unlikely that KMT2C will prove to be the only histone modifier that regulates ERα function, the findings in this report suggest it to be a key regulator of the estrogen responsive phenotype with major implications for hormone therapy of breast cancer." (PMID 29755131, 2018). "Interestingly, data from several large-scale cancer sequencing studies have identified KMT2C (also referred to as MLL3), which encodes an H3K4 histone methyltransferase, as one of the most commonly mutated genes in breast cancer with a mutation frequency of approximately 8%." (PMID 29755131, 2018). "In the presence of E2, KMT2C and KMT2D, together with ER, regulate the expression of the HOXC10 gene and promote breast cancer progression." (PMID 39165358, 2024). "Therefore, we predict that mutations at the amino terminus of KMT2C and KMT2D SET domains might result in the truncation of the SET domain or loss of function of KMT2C and/or KMT2D methyltransferases, subsequently contributing to breast cancer initiation and progression." (PMID 25537518, 2015). "Interestingly, given that KMT2C has been found to regulate estrogen-dependent HOX family gene transcription in chorocarcinoma placenta cells, and identified an estrogen receptor α (ERα) coactivator in breast cancer cells, we observed differential regulation of estrogen response genes." (PMID 32471474, 2020). "Although alterations in KMT2C and FGF19 are common in breast cancer, there is currently no clinical evidence of the correlation between them and the therapeutic effect of breast cancer." (PMID 40994809, 2025).
acute myeloid leukemia (25 papers, 2014 to 2024). Acute myeloid leukemia (AML) is a group of neoplasms arising from precursor cells committed to the myeloid cell-line differentiation. "Mouse studies have also uncovered a tumor suppressor role for KMT2C in acute myeloid leukemia (AML) 12 and urothelial tumorigenesis." (PMID 30665945, 2019). "While KMT2C is identified as a tumor suppressor in acute myeloid leukemia (AML), the role of KMT2D remains unclear in this disease, though its loss promotes B cell lymphoma and various solid cancers." (PMID 37142882, 2023). "KMT2C was already characterized as a tumor suppressor gene in acute myeloid leukemia." (PMID 35664801, 2022). "Finally, a role of KMT2C as a 7q haplo‐insufficient tumor suppressor gene has been proposed in acute myeloid leukemia in mice, by impairing the differentiation of HSPC and cooperating with other established AML lesions." (PMID 33159839, 2021). "Furthermore, rare KMT2C variants have been associated with Kleefstra syndrome, ID, ASD, schizophrenia, non-syndromic primary failure of tooth eruption, and a family with colorectal cancer and acute myeloid leukemia." (PMID 38356881, 2024). "KMT2C and KMT2D function as tumor suppressors in many cancers such as renal cell carcinoma, acute myeloid leukemia (AML), lung adenocarcinoma, and MB." (PMID 39765675, 2024).